MTOR (mechanistic target of rapamycin kinase)
Diseases named in the same sentence as MTOR in open-access papers (continued):
Sharing a sentence is not in itself a finding about the gene and the disease.
upper tract urothelial carcinoma (1 paper, 2015). "This group went on to create a mouse model with a PTEN deletion which resulted in increased AKT/mTOR signaling in upper tract urothelial carcinoma." (PMID 26317352, 2015).
Urethral stricture (1 paper, 2018). Narrowing of the urethra associated with inflammation or scar tissue. "Nevertheless, additional studies are required to confirm and extend our findings and further investigate the relationship between the mTOR and TGF-β signaling pathways in urethral stricture formation." (PMID 29850566, 2018).
urothelial papilloma (1 paper, 2023). A rare benign condition, characterized by a papillary growth in the urinary tract with a central fibrovascular core. "Proteogenomic integration analysis indicates the mutations of HRAS regulated mTOR signaling to form urothelial papilloma rather than papillary urothelial cancer (PUC)." (PMID 37704624, 2023).
urothelium tumor (1 paper, 2025). "Thus, the fact that the effect of amiodarone on mTOR has not been observed in urothelium tumor material is not necessarily surprising." (PMID 40353763, 2025).
uterine disease (1 paper, 2018). "The AMPK, mTOR, AKT, and PI3K metabolic signaling pathways are associated with postpartum metabolic stress, postpartum uterine disease, and changes in endometrial resistance to pathogens." (PMID 29688258, 2018).
uveal cancer (1 paper, 2012). A primary or metastatic malignant neoplasm that affects the choroid, ciliary body, or iris. "In this study, we found that uveal cancer cell fate in response to combined MEK and mTOR inhibition was closely correlated to tumor genotype." (PMID 22808163, 2012).
venous thromboembolism (1 paper, 2025). Occlusion of the lumen of a vein by a thrombus that has migrated from a distal site via the blood stream. "It aids in preventing venous thromboembolism, particularly in patients aged between 40 and 70 years, by inhibiting the mTOR cell pathway, suppressing platelet aggregation, and modulating immune responses, thereby reducing inflammatory markers such as TNF-alpha and IL-6." (PMID 40599143, 2025).
visceral leishmaniasis (1 paper, 2020). A severe form of leishmaniasis characterized by irregular bouts of fever, substantial weight loss, swelling of the spleen and liver, and anemia (which may be serious). "Further in vitro and in vivo investigation will shed light on the contribution of mTOR- and eIF4A-dependent translational programs to the outcome of visceral leishmaniasis." (PMID 32479529, 2020).
Vitreoretinopathy (1 paper, 2021). Ocular abnormality characterized by premature degeneration of the vitreous and the retina that may be associated with increased risk of retinal detachment. "Since TGF-β is involved in mTOR signaling and mTORC1 inhibitor-rapamycin plays a significant role in anti-proliferative properties, it will be interesting to see if rapamycin can be used for treatment purposes in vitreoretinopathy." (PMID 34383767, 2021).
vulvar melanoma (1 paper, 2014). A usually pigmented, nodular or polypoid malignant neoplasm that originates from melanocytes and arises from the vulva.
X-linked agammaglobulinemia (1 paper, 2020). X-linked agammaglobulinemia (XLA) is a clinically variable form of isolated agammaglobulinemia, an inherited immunodeficiency disorder (see this term), and is characterized in affected males by recurrent bacterial infections during infancy. "Fourth, genetic mutations of non-X linked agammaglobulinemia encoding for pre-BCR and/or BCR complex (such as IGHM, CD79a, CD79b, and IGLL1 genes) and for activating mTOR signaling (such as PI3KD and PIK3R1 genes)." (PMID 33013854, 2020).
xanthoma (1 paper, 2023). A non-neoplastic disorder characterized by a localized collection of histiocytes containing lipid. "However, the mechanism underlying enhanced mTOR activation in eruptive xanthomas remains to be elucidated." (PMID 37592976, 2023). "Here, we assessed the activation of mTOR signaling in eruptive xanthomas." (PMID 37592976, 2023). "To determine mTOR signaling activation in eruptive xanthomas, we performed immunohistochemical staining with antibodies against phosphorylated S6 (Ser240/244), 4E-BP1 (Thr37/46), and Akt (Ser473) in eruptive xanthomas (diagnosed by our dermatology clinic) and healthy skin as a control." (PMID 37592976, 2023).
xeroderma pigmentosum (1 paper, 2020). Xeroderma pigmentosum (XP) is a rare genodermatosis characterized by extreme sensitivity to ultraviolet (UV)-induced changes in the skin and eyes, and multiple skin cancers. "Through the Akt/mTOR pathway, xeroderma pigmentosum complementation group C repression rescued cisplatin resistance in LUAD cells." (PMID 31901223, 2020).
cancer (9,786 papers, 2004 to 2026). A tumor composed of atypical neoplastic, often pleomorphic cells that invade other tissues. "As a central regulator of protein synthesis, mTOR links nutrient sensing to cell growth and is frequently implicated in cancer." (PMID 41511947, 2026). "The SV‐associated gene module included key regulators of cancer‐related pathways, such as apoptosis, and the Ras, mTOR, and PI3K‐Akt signaling pathways." (PMID 41536518, 2026). "In osteosarcoma, down-regulated TRIM22 expression led to increased stability of the NRF2 protein and inhibition of the mTOR-associated autophagy signaling pathway, thereby triggering cancer development." (PMID 39759114, 2025). "Intriguingly, cancer‐associated fibroblasts‐secreted IGF‐1 upregulates QSOX2 expression via IGF1R/Akt/mTOR/c‐Myc pathway, establishing a positive feedback loop that sustains ESCC cell stemness." (PMID 40433832, 2025). "Consistent with its central role in controlling cellular growth and proliferation, mutations that activate PI3K/AKT/mTOR signalling are amongst the most common genetic alterations in cancer." (PMID 40360883, 2025). "In this study, VC was shown to decrease the expression of the p13k/Akt/mTOR pathway, which is often associated with the resistance of cancer cells to treatment using endocrine, HER2-directed, or cytotoxic therapies." (PMID 40149617, 2025). "The PI3K/AKT/mTOR pathway, which regulates cell survival, metabolism, and protein synthesis, is commonly activated in cancers via mutations or amplification of PI3K subunits, PTEN loss, or growth factor receptor overexpression." (PMID 41008874, 2025). "Aberrant activation of the AKT/mTOR signaling pathway is often closely associated with cancer development." (PMID 40867281, 2025). "It’s role in tumorigenesis highlights the potential of PI3K/Akt/mTOR inhibitors not only in treating cancer but also in alleviating associated pain." (PMID 40579593, 2025). "Downregulation of BAG3 is linked to reduced activation of the PI3K/Akt/mTOR pathway, and its abnormal expression is involved in cancer progression." (PMID 40863727, 2025). "One major challenge is the development of resistance, which occurs when cancer cells acquire mutations or alter signaling pathways to bypass mTOR inhibition." (PMID 39762538, 2025). "Inhibition of mTOR by CR also promotes cellular quiescence, limiting excessive proliferation—a hallmark of cancer." (PMID 39940361, 2025). "Poly(lactic-co-glycolic acid) (PLGA) nanoparticle-encapsulating medications, like doxorubicin, block the AKT/mTOR pathway, hence inducing autophagy and increasing cancer cell susceptibility to treatment." (PMID 40076496, 2025). "The results indicate that mouse and human samples with different mTOR activation levels are involved in key cellular processes associated with cancer hallmarks." (PMID 41218079, 2025). "While mTOR’s role in normal physiology is critical, its dysregulation is also implicated in various pathological states, including cancer, metabolic disorders, and neurodegenerative diseases." (PMID 41301687, 2025). "PI3K/Akt/mTOR interacts with numerous other cellular signaling pathways, and its deregulation is associated with the development and progression of many types of cancer." (PMID 40647529, 2025). "Mutation in the STK11 gene in A549 cells potentiates cancer hallmarks, such as deregulation of cellular metabolism, aside from the Warburg effect, mTOR activation, autophagy inhibition, and NRF2 and redox activation." (PMID 39955067, 2025). "In various cancer types, the mTOR complex is often over-activated due to the loss of tumor suppressors like phosphatase and tensin homologue (PTEN), activation of oncogenes such as phosphoinositide 3-kinase (PI3K) and metabolic reprogramming." (PMID 39940704, 2025).
cancer (continued). "Inhibiting SREBP1 or SCD1 makes cancer cells with PI3K/AKT/mTOR mutations more susceptible to ferroptosis." (PMID 40740483, 2025). "Given the prevalence of mTOR mutations in an assortment of cancers, mTOR pathway inhibitors have been developed and are currently being used." (PMID 40943615, 2025). "The AKT/mammalian target of rapamycin (mTOR) signaling pathway is one of the most frequently mutated pathways in CRC that prevents cancer cells from oxidative stress and ferroptosis." (PMID 41234632, 2025). "Given the therapeutic potential of mTOR inhibition in FA− deficient cancers, understanding the mechanistic basis of this sensitivity is of both biological and clinical significance." (PMID 40805278, 2025). "According to studies, downregulation of the PI3K/AKT/mTOR pathway can enhance ferroptosis induction in cancer cells, especially those with PI3K mutations or PTEN deficiency, by downregulating downstream factors such as GPX4, SREBP1, and SLC7A11." (PMID 40740483, 2025). "AKT1, a serine/threonine kinase belonging to the AKT subfamily, is a well-characterized effector of PI3K in the PI3K/AKT/mTOR signaling pathway, and its dysregulation is implicated in many types of human cancers." (PMID 38243957, 2025). "The downregulation of these pathways is known to inhibit cancer cell proliferation and is closely associated with mTOR signaling." (PMID 40855114, 2025). "The PI3K/Akt/mTOR pathway is frequently associated with resistance to cancer therapies, enabling dormant cells to survive initial treatments and later contributing to disease relapse." (PMID 39934876, 2025). "mTOR regulates cell growth, proliferation, and survival, and its activation is linked to enhanced cancer cell motility and invasion." (PMID 40964608, 2025). "Cancers with elevated mTOR signaling are often more susceptible to mTOR inhibition, and EHE cells appear to have elevated PI3K-AKT-mTOR signaling." (PMID 40940986, 2025). "Specific mTOR SNPs, such as rs1883965, rs1034528, and rs17036508, are linked to lower mTOR transcript levels and an increased risk of cancer." (PMID 39940361, 2025). "These mutations have been associated with decreased apoptosis and have been shown to activate the PI3K/AKT/mTOR pathway, which is potentially involved with tumor progression and has been associated with tumorigenesis of other cancer types." (PMID 40710211, 2025). "For instance, PI3K/mTOR pathway is the most aberrantly activated cancer‐associated signaling pathway with more than a 90% prevalence in head and neck malignancy." (PMID 40385549, 2025). "Dysregulation of this pathway is implicated in numerous human diseases, underlining the importance of understanding mTOR-driven tumorigenesis as a crucial objective in cancer therapy." (PMID 40855114, 2025). "Aberrant activation of PI3/AKT/mTOR causes activation or suppression of various protein molecules in numerous cancers, representing it as attractive therapeutic targets in multiple malignancies." (PMID 40676293, 2025). "Loss of tumor suppressor phosphatase and tensin homolog (PTEN) or tuberous sclerosis complex 2 (TSC2) activates mTOR signaling pathway and is associated with various cancers." (PMID 39863613, 2025). "High blood sugar and insulin levels activate growth-promoting pathways, such as PI3K/Akt/mTOR, in colon cells, which increases the risk of cancer." (PMID 41374093, 2025). "Activation of the PI3K/AKT/mTOR has been found to occur independently of upstream regulators and is linked to poor cellular differentiation, increased motility, invasiveness, and cancer stem cell‐like characteristics." (PMID 40740483, 2025).
cancer (continued). "mTOR is a key cellular regulator that senses nutrients and energy to control growth, metabolism, and survival, with dysregulation linked to diseases like cancer and diabetes." (PMID 40944200, 2025). "One of the downstream effectors of Akt, the mechanistic target of rapamicyn (mTOR) associates several other proteins involved in cancer progression." (PMID 40963621, 2025). "TSC2 mutations or deletions are associated with numerous cancers and have been identified as critical drivers in tumor types with heightened mTOR pathway activity." (PMID 41181577, 2025). "Designed by linking an FRB-binding moiety to a TORKI structure, RapaLink-1 is able to overcome resistance in cancer cells that harbor mutations in either the FRB or kinase domains of mTOR." (PMID 41469379, 2025). "Persistent activation of mTOR signaling is closely linked to tumor growth, proliferation, and survival in many types of cancer." (PMID 40438606, 2025). "An in vitro study in oral cancer reported that MTF inhibits cell proliferation and regulates cancer‐associated pathways affecting mTOR and mitochondrial activity." (PMID 40385549, 2025). "It is linked to the mTOR pathway and the development and progression of cancer as well as therapy resistance." (PMID 41429766, 2025). "In CSCs, PI3K/AKT/mTOR pathway has been associated with attribution of various properties to cancer cells including stemness characteristics, proliferation, migration, epithelial to mesenchymal transition, and autophagy." (PMID 40676293, 2025). "Activation of PI3K/AKT/mTOR signaling promotes the Warburg effect, a metabolic reprogramming often associated with cancer development and aggressiveness." (PMID 41009024, 2025). "Suppressing mTOR signaling has shown the ability to decrease cancer's susceptibility to chemotherapy while also inducing ER stress." (PMID 40769273, 2025). "The PI3K/AKT/mTOR pathway is crucial in regulating keyprocessesin mammalian cells, and impairments of this pathway are associatedwith cell survival in several cancer types." (PMID 41048819, 2025). "They found a strong correlation between the hallmarks of polyploidy and mTOR signaling, along with its association with cancer, aging and diabetes." (PMID 40117022, 2025). "Sulforaphane, derived from cruciferous vegetables like broccoli and cauliflower, has demonstrated mTOR inhibitory effects and is associated with the mechanisms involved in reduced cancer cell proliferation." (PMID 40717210, 2025). "CS is the result of dysregulation of the MTOR pathway contributing to cellular proliferation, which leads to an increased risk for the development of benign and malignant tumors of the breast, thyroid, endometrium, and kidney." (PMID 41180948, 2025). "Aberrant mTOR signaling is a hallmark of many cancers and is associated with increased tumor progression." (PMID 40080721, 2025). "The mTOR pathway plays a vital role in regulating cell growth, metabolism, and survival and is closely associated with cancer progression." (PMID 40075606, 2025). "Despite the high prevalence of mTOR-mutated cancers, solo and combo treatments using rapalogs or mTOR kinase inhibitors have shown at best mixed results." (PMID 40943615, 2025). "The PI3K/AKT/mTOR pathway regulates cell survival, growth, and metabolism, and is abnormally activated or deregulated in most human cancers; it is associated with anti-apoptosis and pro-survival properties." (PMID 40260390, 2025). "The PI3K/AKT/mTOR signaling pathway plays a central role in cellular growth, proliferation, and survival, making its dysregulation a hallmark of various cancers and a critical target for therapeutic intervention." (PMID 40927720, 2025).